ZNF830 (zinc finger protein 830)
Description:
May play a role in pre-mRNA splicing as component of the spliceosome. Acts as an important regulator of the cell cycle that participates in the maintenance of genome integrity. During cell cycle progression in embryonic fibroblast, prevents replication fork collapse, double-strand break formation and cell cycle checkpoint activation. Controls mitotic cell cycle progression and cell survival in rapidly proliferating intestinal epithelium and embryonic stem cells. During the embryo preimplantation, controls different aspects of M phase. During early oocyte growth, plays a role in oocyte survival by preventing chromosomal breaks formation, activation of TP63 and reduction of transcription (By similarity).
Synonyms: CCDC16; MGC20398; OMCG1
Tractability: PROTAC: its protein half-life has been measured.
Gene: Protein-coding gene on chromosome 17 (34,961,540 to 34,963,777, forward strand). Ensembl gene ENSG00000198783.
Subcellular location: Nucleus; Chromosome; Nucleus speckle
Subcellular location (Human Protein Atlas): Nucleoplasm
Pathways (Reactome):
DNA Repair: Dual incision in TC-NER; Formation of TC-NER Pre-Incision Complex; Gap-filling DNA repair synthesis and ligation in TC-NER; Transcription-Coupled Nucleotide Excision Repair (TC-NER)
Metabolism of RNA: mRNA Splicing - Major Pathway
Gene Ontology:
Molecular function: protein binding; nucleic acid binding; zinc ion binding
Biological process: mRNA splicing, via spliceosome; mitotic DNA replication checkpoint signaling; negative regulation of apoptotic process; ovarian follicle development; preantral ovarian follicle growth; RNA processing
Cellular component: nucleoplasm; nucleus; spliceosomal complex; chromosome; nuclear speck
Genetic constraint (gnomAD): Loss-of-function variants: 15 observed, 30 expected, observed/expected ratio (o/e) 0.5, 90% interval 0.33 to 0.77. The upper end of that interval is the gene's LOEUF score, 0.77, which puts it in group 3 of 6, group 1 being the genes least tolerant of losing a copy. Missense variants: 456 observed, 501.98 expected, observed/expected ratio (o/e) 0.91, 90% interval 0.84 to 0.98. Synonymous variants: 208 observed, 201.16 expected, observed/expected ratio (o/e) 1.03, 90% interval 0.92 to 1.16.
Homologues: Orthologues: chimpanzee ZNF830 (99% identical), macaque ZNF830 (97% identical), dog ZNF830 (87% identical), pig ZNF830 (85% identical), guinea pig ZNF830 (85% identical), rat Zfp830 (85% identical), rabbit ZNF830 (83% identical), mouse Zfp830 (83% identical), Drosophila melanogaster CG11839 (21% identical), Caenorhabditis elegans sel-13 (18% identical).
Diseases named in the same sentence as ZNF830 in open-access papers:
ZNF830 is named in the same sentence as 8 diseases in open-access papers, as found by Europe PMC text mining. Sharing a sentence is not in itself a finding about the gene and the disease. The quoted sentences say what the papers report.
lung carcinoma (2 papers, 2019 to 2022). "A recent study demonstrated that zinc finger protein 830 (ZNF830) plays a role in the repair of DNA double-strand breaks and that knockdown of ZNF830 sensitizes lung cancer cells to olaparib, a DNA-damaging agent." (PMID 31861937, 2019). "In accordance with its role in HR, ZNF830 depletion sensitized lung cancer cells to IR, HU and CPT and also led to olaparib sensitivity in lung cancer cells and xenografts." (PMID 35205626, 2022).
glioblastoma (1 paper, 2020). The most malignant astrocytic tumor (WHO grade IV). "Additionally, knockout of PAG1 or ZNF830 in GSCs delayed the onset of neurological signs in orthotopic glioblastoma xenografts compared to GSCs treated with a non-targeting sgRNA." (PMID 32499560, 2020).
non-small cell lung carcinoma (1 paper, 2024). A group of at least three distinct histological types of lung cancer, including non-small cell squamous cell carcinoma, adenocarcinoma, and large cell carcinoma. "In a xenograft model of non-small cell lung cancer, depletion of ZNF830 was able to dramatically inhibit tumor growth in combination with treatment with the PARP inhibitor, Olaparib, although it remains to be seen whether targeting ZNF830 in established tumors will have similar effects." (PMID 39119040, 2024).
cancer (2 papers, 2021 to 2025). A tumor composed of atypical neoplastic, often pleomorphic cells that invade other tissues. "For instance, ZNF830 promotes homologous-recombination repair and mediates cancer chemoresistance; ZNF281 acts as a potential diagnostic marker for oral squamous cell carcinoma; and ZNF419 might serve as a potential prognostic and immunological pan-cancer biomarker." (PMID 40599863, 2025).
ZNF830 also shares sentences with these, for which no sentence is quoted: gastric cancer (1 paper); glioma (1); tumor (1); ZIKV infection (1).